IL1A (interleukin 1 alpha)
Diseases named in the same sentence as IL1A in open-access papers (continued):
Sharing a sentence is not in itself a finding about the gene and the disease.
cancer (continued). "Moreover, IL-1R signaling through the expression of inflammatory mediators promotes cancer cell survival and stemness development (both IL-1β and IL-1α reprogram mesenchymal stem cells secrete β-catenin-inducing factors), creating a cancer stem cell niche." (PMID 39201656, 2024). "IL-1α/IL-1β cytokines promote cancer phenotypes and contribute to resistance in cancer treatment." (PMID 37789138, 2024). "IL‐1A is crucial for the development, invasion and metastasis of cancer." (PMID 38152044, 2024). "IL-1α enhances cancer progression by upregulating the expression of the SASP factor." (PMID 38003589, 2023). "This study assessed IL-1α as a drug to bolster platelet levels in cancer patents." (PMID 37928695, 2023). "In the present study, we have shown that the intake of carrot juice decreased the secretion of a central cytokine in inflammation related to cancer development: IL-1α and IL-16 in blood samples stimulated with LPS ex vivo, although only one sample was obtained from each subject." (PMID 36771338, 2023). "In the Th1 environment, pro-inflammatory cytokines IL-1α, IL-1β, and IL-6 may participate in cancer eradication by recruiting white blood cells from the circulation and stimulating cells." (PMID 37893233, 2023). "Several clinical reports describe intravenous infusion of IL-1α in cancer patients." (PMID 37928695, 2023). "Moreover, high expression of IL1α significantly increased the lung colony numbers of the 231‐GFP cells (2.0‐fold) in the nude mice injected with cancer cells through tail vein injection." (PMID 37551997, 2023). "In contrast, after pretreating ECs with IL1a, all cancer cells could form dynamic adhesions with mostly firm adhesions and rolling events irrespective of the sLeA/X status." (PMID 37486674, 2023). "However, IL-1α exerts pro- and anti-cancer effects; hence its involvement in cancer progression is still controversial." (PMID 37580647, 2023). "We then analyzed how dysregulation of IL-1α induced by Spalax CM affects cancer cell migration." (PMID 36982207, 2023). "We further found that the expression of GDF15 but not IL1A was positively associated with the logIC50 of sunitinib using Genomics of Drug Sensitivity in Cancer (GDSC) and Cancer Genome Project (CGP) datasets." (PMID 36720918, 2023). "In line with these previously reported functions of IL-1α in cancer, M1 cells that exhibit increased IL-1α production also demonstrate enrichment in processes such as angiogenesis and blood vessel morphogenesis, positive chemotaxis, and the regulation of macrophage and leukocyte chemotaxis." (PMID 37835389, 2023). "Both IL-1α and IL-1β play pro-tumorigenic roles in several cancers." (PMID 35086565, 2022). "We found similarities in pathways and upstream regulators of FOXO3-deficient macrophages with HFD obese mice colon associated with inflammation (IL-1A, IL-1B, IL-6, IL-8 signaling), growth (ILK signaling, CDK5 signaling, VEGF signaling) and cancer (cAMP-mediated signaling)." (PMID 35323693, 2022). "Moreover, the use of an IL-1α-blocking monoclonal antibody in clinical trials has shown its potential as a therapeutic activity for advanced cancer patients." (PMID 35740551, 2022). "Accumulating evidence suggests IL-1α is involved in cancer pathogenesis." (PMID 33430381, 2021). "In addition, IL‐1α/β are also key proinflammatory cytokines produced by cancer cells and immune cells, which are NF‐κB‐dependent and promote the activation of NF‐κB and MAPK pathways and tumorigenesis." (PMID 34977871, 2021). "Therefore, we demonstrate that IL1A-induced CCL2 and IL8 expression directly or indirectly associated with cancer metastasis in TNBC cells." (PMID 34203721, 2021). "Although IL-1β and IL-1α share similar transducing pathways, they have different expression and activation processes, explaining why they have different biological and physiological effects in many diseases, notably cancer." (PMID 32635472, 2020).
cancer (continued). "As IL1A/B expression levels were significantly greater in the highly metastatic MDA-LM2 cancer cells compared with the MDA parental cells, we hypothesized that this may be due to higher JNK activity." (PMID 32198421, 2020). "Indeed, isolated CXCR3+ cancer cells expressed higher levels of IL1A/B compared with CXCR3− counterparts, and CM from CXCR3+ MDA-LM2 cells contained higher levels of secreted IL-1α/β." (PMID 32198421, 2020). "We therefore reasoned that CXCR3+ cancer cells may secrete higher levels of IL-1α/β, in turn leading to elevated production of CXCL9/10 in fibroblasts." (PMID 32198421, 2020). "Further work in this field will identify whether mechanisms for neutralizing IL-1α can be optimized and made viable for cancer therapy." (PMID 31231372, 2019). "However, there is still a wealth of literature that suggests IL-1α can play a role in mediating angiogenesis, most predominantly in cancer and in the brain." (PMID 31293586, 2019). "In the same study, the authors also showed that as a result of silencing IL-1A in pancreatic tumour cells (PaTu), CCL22 production was inhibited in PBMC, whereas inhibition of IL-1A or IL-1B in mammary 4T1 cancer cell line resulted in impaired CCL22 production in splenocytes." (PMID 29760166, 2018). "Previous studies have shown that down regulating the expression of IL-1α could inhibit or attenuate cancer progression, especially for colorectal cancer." (PMID 29162930, 2017). "With regard to human cancers, high levels of released IL-1α is a marker for poor prognosis." (PMID 28900035, 2017). "Moreover, conditioned medium from IL-1α-stimulated PSCs further enhanced cancer cell migration compared to both control medium and conditioned medium from unstimulated PSCs." (PMID 27473228, 2016). "We describe the allelic distributions of four IL1A (rs3783553), IL4 (rs79071878), NFKB1 (rs28362491) and PAR1 (rs11267092) gene polymorphisms, which the literature describes as polymorphisms with a risk of cancer or worse prognosis for cancer." (PMID 26879815, 2016). "IL-1α may promote cancer progression by stimulating angiogenesis; IL-1α may also promote epithelial repair and prevent CAC by inducing the expression of cyclooxygenase 2 (COX-2), a key enzyme of prostaglandin E2 (PGE2) synthesis from arachidonic acid (AA)." (PMID 26823956, 2016). "TGFβ signaling suppressed IL-1α mediated pancreatic stellate cell induced carcinoma cell migration." (PMID 27473228, 2016). "NF-κB pathway plays an important role in regulating cancer cells proliferation, anti-apoptosis, invasion and metastasis and angiogenesis, through modulating series of functional genes expression and activity, including IL1A, CCND1, MYC, Bcl-2, MMP9 and VEGF." (PMID 26429874, 2015). "Because IL-1α expression was augmented in the highly metastatic cancer cells and tumors, we examined whether IL-1/IL-1R signaling was involved in the high angiogenic and lymphangiogenic potential of LNM35 tumors." (PMID 24924428, 2014). "However, it is worth to note that Ad vector-mediated IL-1α production is beneficial for vaccine development or cancer gene therapy." (PMID 25551570, 2014). "Better understanding of the integrative role of IL-1α and IL-1β in distinct malignancies will facilitate the application of novel IL-1 modulation approaches at the bedside, in cancer patients with minimal residual disease (MRD), as an adjunct to conventional approaches to reduce the tumor burden." (PMID 23847618, 2013). "Interestingly, the expression of IL-1α mRNA in fibroblasts by various cancer cell–conditioned media was comparable with IL-6 production by the same conditioned media." (PMID 23593346, 2013). "Consequently, the inhibition of signaling pathways leading to IL-1α expression and/or neutralization of IL-1α in the PDAC microenvironment should be taken into consideration as a possible treatment or as a complement to existing treatments of this cancer." (PMID 23951028, 2013).
cancer (continued). "The observation that the level of 11βHSD-2 mRNA is more greatly increased in response to IL-1α in cancer cell lines relative to HOSE cells may suggest that expression of IL-1R is not limiting the effects of IL-1α on gene expression in the cancer cell lines." (PMID 15870720, 2005). "Therefore, regulating IL-1α concentrations in the cancer microenvironment is imperative." (PMID 40940885, 2025). "To broaden the scope of our study of the IL-1α/IL-1R1 axis of age-enhanced emergency myelopoiesis, we wanted to determine whether this proposed mechanism for aging-driven cancer progression is relevant to other cancer settings." (PMID 39236155, 2024). "The factor responsible for this process may be IL-1α secreted by cancer cells." (PMID 37408240, 2023). "Therefore CPH:SA formulations may be promising as delivery vehicles for IL‐1α to achieve safe and effective antitumor responses for cancer patients." (PMID 37206237, 2023). "Thus, IL‐1α‐driven processes can play a dual role during cancer, which is likely context‐dependent." (PMID 36175368, 2023). "IL-1α has been implicated in cancer pathogenesis, but there is little evidence of its role in GBM." (PMID 35626018, 2022). "It includes seven ligands with pro-inflammatory activity (IL-1α, IL-1β, IL-18, IL-33, IL-36α, IL-36β, IL-36γ), as well as anti-inflammatory cytokines (IL-37 and IL-38), having crucial roles in host-defense responses, but also in inflammatory responses that contribute to cancer development." (PMID 33840390, 2021). "Thus, it is crucial to reveal the detailed roles of IL-1α isoforms in different cancer types as well as the mechanisms of their processing and regulation in order to discover new drug candidates that can target IL-1α functions more precisely for future immunotherapy." (PMID 33430381, 2021). "Cancer cells treated with recombinant IL1α or IL1β upregulate the expression of those same cytokines, suggesting that secretion of IL1α or IL1β in a few cancer cells could lead to the upregulation of both cytokines in neighboring cancer cells." (PMID 29777109, 2018). "Allelic variants of the interleukin 1A (IL1A), interleukin 4 (IL4), nuclear factor kappa B1 (NFKB1) and protease-activated receptor 1 (PAR1) genes may influence not only the inflammatory response but also susceptibility to cancer development." (PMID 26879815, 2016). "These known NF-κB target genes, such as IL6, IL8, BIRC2 (clAP-1), ICAM1, YAP1, CDKN1A (p21), CSF2, CCDN1, IL1A, IL1B, and so on, include many that have been independently confirmed to be differentially expressed and pathologically implicated in HNSCC and other cancers." (PMID 18334025, 2008). "In complete responders, skin lesion RNA sequencing after treatment, compared with baseline, identified increased inflammation (CXCL5, CXCL8, IL1A, COL1A1) and downregulated cancer markers (PRAME, S100B, MLANA, STK32A)." (PMID 42316430, 2026). "In our study, the treatment of non-aggressive BCC with CM derived from MpEV-ATMSC induced the expression of IL6, IL8, and IL1α in these BCC, suggesting the involvement of the PGE2 signaling pathway in the ability of MpEV-ATMSC to induce cancer stemness." (PMID 38515582, 2024). "We found that IFNA1 and IFNL1 gene transcripts resulted negligibly expressed across the pan-cancer dataset when compared to other immunosuppressive and pro-inflammatory cytokines such as TGFB1/2, PTGES2, IL1A, IL1B, IL6 and CSF1." (PMID 38239354, 2023). "Our own studies confirm the influence of cytokines (i.e., concentrations of IL-1A, IL-1B, IL-2, IL-6, IL-10, TNF, and IL-4) on the emergence of fatigue in all its dimensions in patients with cancers of the reproductive organs at various stages of treatment." (PMID 36834426, 2023). "In the early stage of CRLM, the adherence of disseminated cancer cells to KCs prompts KCs to capture and phagocytose the cancer cells and release TNF-α, interleukin-1α (IL-1α) and IL-1β, thus reducing the metastasis of colon cancer cells to the liver." (PMID 37480104, 2023).
cancer (continued). "Interleukin 1 alpha (IL1A) and interleukin 1 beta (IL1B) belong to the IL-1 protein cluster and are involved in chronic inflammation, as well as in cancer development." (PMID 37189693, 2023). "IL-1α and LIF display cooperative effects in activating EMH and are both up-regulated in some human cancers." (PMID 37134077, 2023). "CD44+/CD24−/low BCSC play a crucial role in cancer invasion, as cell lines with a higher proportion of CD44+/CD24−/low cells exhibit greater expression of pro-invasive genes, such as interleukin-1 alpha (IL1α), interleukin-6 (IL6), and interleukin-8 (IL8)." (PMID 37445860, 2023). "The levels of cytokines such as IL1a, IFNB1, CD80, CD86, and CXCL10, which are important for inducing an immune response by macrophages within cancer tissue, were upregulated in PBMCs in a RIG-I-dependent manner." (PMID 37543704, 2023). "It is possible that cancer cells and myeloid cells express IL-1Ra in PDA to effectively counteract IL-1α-mediated senescence signaling." (PMID 37563620, 2023). "The amount of TGF-β was significantly higher than IL-1α and IL-1β in AGS and SW480 cancer cell media." (PMID 35265687, 2022). "In the present study, we detected the levels of IL-1α, IL-1β, and TGF-β in AGS and SW480 cancer cell media and found that TGF-β level was increased significantly in both cancer cell media." (PMID 35265687, 2022). "Univariate Cox regression analysis identified four genes (CCNB1, CCNA2, IL1A, and MMP3) that significantly affected patient survival based on the 27 anticolon cancer targets of THCQF." (PMID 35479514, 2022). "IL1A and IL1B are key cytokines that regulate inflammation and influences TME, thus promoting the origin and progression of various cancers." (PMID 35296025, 2022). "Several of those, such as members of the TNF-α superfamily, Interleukins (IL)-1α, -1β, -6, -8 and members of the Transforming Growth Factor (TGF)—β superfamily, have been also recognized to affect anti-cancer immunity." (PMID 35743911, 2022). "Furthermore, the detailed function of IL-1A may be related to the type of cancer." (PMID 36071472, 2022). "OSCC cells can release IL-1α that stimulates CAF proliferation, concomitantly CAF increases the secretion of CCL7, CXCL1, and IL-8 cytokines that help facilitate cancer progression and invasion." (PMID 33430381, 2021). "We have previously reported that hWJSC-CM contains significantly higher levels of interleukins and adhesion molecules like IL-1a, IL-6, IL-8, HGF, SCF, and MCP-1 that regulate cancer cell death and modulate the immune system." (PMID 32377203, 2020). "Research emphasizes the critical role of humoral factors secreted by cancer cells in the patient’s tissues in the regulation of processes leading to cachexia, which also include pro-inflammatory cytokines IL-6, TNF-α, IFNγ, IL-1α, and IL-1β." (PMID 33158194, 2020). "The oncogenic signal activates two parallel pathways, namely the MAPK and NF-κB pathways, involving IL-1α stimulation, to enhance the expression of CD137 in cancer cells." (PMID 31288851, 2019). "Serum of mice that had received cancer cells secreting IL-15sol showed significantly elevated levels for Eotaxin, G-CSF, IFN-γ, IL-1α, IL-5, IL-6, IP-10, KC, MCP-1 and MIG." (PMID 31856922, 2019). "Antioxidants such as N-acetylcysteine (NAC) and catalase are able to prevent the ANE- and arecoline-induced toxic events such as COX-2 expression, PGE2, IL-1α, cytotoxicity etc. as well as MMP-9 secretion of SAS cancer epithelial cells in this study." (PMID 31831717, 2019). "Thus, IL-1α may be a particularly important target for the treatment of cancer." (PMID 31182982, 2019). "The same miRNA then regulates IL1A, known to influence PLAU with regard to cancer invasion and metastasis." (PMID 28824643, 2017). "BRD4, mTOR, IL-1α and additional regulators of SASP are potential targets for anti cancer treatment." (PMID 28966805, 2017).
cancer (continued). "Together, these results reveal that IL1α, IL1β and GCLM are critical downstream mediators of H3 ubiquitination signalling in cancer regulation." (PMID 28300060, 2017). "IL-1α inhibition by IL-1RA or IL-1α-neutralizing antibodies reduced the inflammatory PSC profile and inhibited cancer cell migration." (PMID 27473228, 2016). "Again in the second experiment, human biofield treatment (TT2) significantly decreased IL-1β, IL-1α, MIP-2, and MIG from high levels with cancer to control/PBS levels." (PMID 26113869, 2015). "Necroptosis, IL-1α release, and enhancement of DC activation were dependent on the expression of RIPK3 in cancer cells." (PMID 25888634, 2015). "TT produced significant effects in IL-1α, IL-1β, MIP-2, and MIG, which were upregulated with cancer and brought down to control (PBS) levels." (PMID 26113869, 2015). "Of 11 markers previously affected, 7 markers significantly changed in the same manner: IL-1β, IL-1α, IFN-γ, MIP-2, IL-2, MIG, and IP-10, with cancer (CA2)." (PMID 26113869, 2015). "IL-1β, IL-1α, MIP-2, and MIG were upregulated by cancer and downregulated to control levels (PBS-treated mice) by TT." (PMID 26113869, 2015). "The most up-regulated genes in U87 cells were interleukins and receptors (IL1A, IL13RA2, IL1RN), CT45A5 from the cancer/testis (CT) family of antigens, and the cytoplasmic transporter ATP6V0D2." (PMID 25481245, 2014). "We then measured the expression of IL-1 proteins (IL-1α and IL-1β), CXCL8/IL-8, and VEGF family proteins (VEGF-A, -C, and -D) in cancer cells and/or tumor stromal macrophages in lower and highly metastatic tumors." (PMID 24924428, 2014). "Since macrophages accumulate in both tissues, in adipose tissue in MO and cancer tissue in CRC patients, elevated IL-1α concentrations are unsurprising in both our groups." (PMID 23173608, 2012). "In the current study, we demonstrate that hBD-3 can promote macrophage expression of IL-1α, IL-6, IL-8, and CCL18; i.e., cytokines and chemokines that are produced by TAMs as components of the cancer-related inflammation." (PMID 20544025, 2010). "Functional assays showed that IL-1α knockdown significantly impaired cancer cell migration without affecting their proliferation." (PMID 40940885, 2025). "Notably, siRNA-mediated suppression of IL-1α in HSC3 cells impaired migration while leaving proliferation unaffected, highlighting its functional role in promoting cancer cell motility." (PMID 40940885, 2025). "Current research on pro-inflammatory cytokines explains that IL-1A, IL-1B, IL-6, TGF-β1, and IFN-γ might be key components of the PeCa TIME and are believed to play a significant role in cancer formation." (PMID 40141426, 2025). "In additional experiments, where we compared healthy mice to 4PYR-treated animals, we found that 4PYR has contributed to significantly increased expression of cytokines related to inflammation and cancer progression, such as CCL3, CXCL1, CCL5 or IL-1A and IL-1B." (PMID 39795893, 2024). "Our experiments demonstrated that treatment with some of the components of OA such as IL-1α and COMP was not the sole contributing factor causing the cancer to grow and migrate." (PMID 38892202, 2024). "The identified up-regulated genes with H3K27Ac engagement included the inflammatory response genes IL1α, IL1β, and SERPINB2; the HBEGF gene that mediates cell migration and invasion; PLAU, which is regulated by AP-1 and drives cancer metastasis; and LAMC2, which is involved in the EMT process." (PMID 37511268, 2023). "Collectively, we propose the parallel mechanisms of IL-1α and LIF that can synergize to activate splenic HSC niche to increase PMN production that may function in human cancers." (PMID 37134077, 2023). "However, co-treatment of Spalax CM with recombinant IL-1α agonist diminished the effect of Spalax CM and restored MDA-MB-231 cancer cells migration." (PMID 36982207, 2023).